FAM3B (FAM3 metabolism regulating signaling molecule B)
Description:
Induces apoptosis of alpha and beta cells in a dose- and time-dependent manner.
Synonyms: PANDER; C21orf11; C21orf76; PRED44; D21M16SJHU19e; 2-21; ORF9
Tractability: Antibody: UniProt places it where antibodies can reach, with medium confidence; UniProt predicts a signal peptide or a membrane-spanning region; its Gene Ontology location is reachable by antibodies, with medium confidence.
Gene: Protein-coding gene on chromosome 21 (41,304,212 to 41,357,727, forward strand). Ensembl gene ENSG00000183844.
Subcellular location: Secreted
Subcellular location (Human Protein Atlas): Vesicles; Predicted to be secreted
Gene Ontology:
Molecular function: protein binding; cytokine activity
Biological process: insulin secretion; signal transduction
Cellular component: extracellular exosome; extracellular region
Genetic constraint (gnomAD): Loss-of-function variants: 20 observed, 23.78 expected, observed/expected ratio (o/e) 0.84, 90% interval 0.59 to 1.22. The upper end of that interval is the gene's LOEUF score, 1.22, which puts it in group 5 of 6, group 1 being the genes least tolerant of losing a copy. Missense variants: 216 observed, 239.55 expected, observed/expected ratio (o/e) 0.9, 90% interval 0.81 to 1.01. Synonymous variants: 79 observed, 84.81 expected, observed/expected ratio (o/e) 0.93, 90% interval 0.78 to 1.12.
Homologues: Orthologues: chimpanzee FAM3B (98% identical), pig FAM3B (77% identical), mouse Fam3b (76% identical), rat Fam3b (75% identical), dog FAM3B (71% identical), guinea pig Fam3b (61% identical), tropical clawed frog fam3b (48% identical), Caenorhabditis elegans famp-1 (29% identical). Paralogues in human: FAM3C (33% identical), FAM3A (32% identical), FAM3D (31% identical).
Diseases named in the same sentence as FAM3B in open-access papers:
FAM3B is named in the same sentence as 42 diseases in open-access papers, as found by Europe PMC text mining. Sharing a sentence is not in itself a finding about the gene and the disease. The quoted sentences say what the papers report.
diabetes (6 papers, 2017 to 2025). "As a result, FAM3B is associated with several significant disorders, including diabetes, AD, and cancer." (PMID 40294019, 2025). "Among the highly probable genes involved in the pathogenesis of diabetes in GK rat, it has been demonstrated that the overexpression or inhibition of Fam3b, Ptprn2, Ide, Hnf4g, Bad and Bmp4 is associated with the glucose tolerance in rodents." (PMID 30687391, 2018). "However, the genes Bmp4, Fam3b, and Ptprn2 were found to be associated with diabetes in GK rats for the first time in the present study." (PMID 30687391, 2018). "Given that the increasing incidence of diabetes and subsequent vascular diseases is currently a major public health problem in industrialized countries, inhibition of FAM3B expression in VSMCs may be beneficial for the prevention and therapy of diabetes-associated cardiovascular complications." (PMID 28536423, 2017). "Here, we report for the first time that Fam3b, Ptprn2 and Bmp4 are related to diabetes in GK rats." (PMID 30687391, 2018). "Thus, FAM3B may therefore serve as a novel therapeutic target for diabetes-related CVDs." (PMID 28536423, 2017).
Insulin resistance (5 papers, 2014 to 2022). Increased resistance towards insulin, that is, diminished effectiveness of insulin in reducing blood glucose levels. "Moreover, Fam3b transgenic mouse overexpressing Fam3b exclusively in the endocrine pancreas exhibited glucose intolerance and insulin resistance." (PMID 30687391, 2018). "PANDER (FAM3B) is processed by cleaving the signal peptide and then secreted from pancreatic alpha and beta cells, and secreted PANDER induces hepatic insulin resistance." (PMID 29285313, 2017).
type 2 diabetes (5 papers, 2010 to 2022). "Therefore, FAM3B plays an important role in the progression of type 2 diabetes by negatively regulating islet function and insulin sensitivity in the liver." (PMID 28536423, 2017).
colon carcinoma (4 papers, 2017 to 2019). "Interestingly, the transcription factor SLUG is targeted by FAM3B to promote epithelium mesenchymal transition (EMT) in colon carcinoma cells and inhibition of FAM3B by RNAi is associated to decreased Bcl-2 in colon tumor cells." (PMID 29357840, 2018). "In contrast, stable overexpression of FAM3B-258, a non-secretory form of FAM3B, in colon cancer cells led to increased expression levels of Slug and Cdc42 and promoted cell migration and invasion in vitro and metastasis in nude mice." (PMID 28536423, 2017).
gastric cancer (4 papers, 2014 to 2025). A primary or metastatic malignant neoplasm involving the stomach. "Several studies have shown that high expression of FAM3B promoted progression in the colon, prostate, and esophageal cancer and drug resistance in gastric cancer." (PMID 36172369, 2022). "In 2008, Huang et al17 first reported that the expression level of FAM3B was lower in human gastric cancer tissues than in adjacent normal tissues and that its lower mRNA level was associated with deeper tumour invasion of gastric cancer tissues." (PMID 30565387, 2019). "Furthermore, FAM3B promoted epithelial-mesenchymal transition (EMT) in gastric cancer cells by upregulating snail protein." (PMID 40110195, 2025). "However, FAM3B, also known as PANcreatic DERived factor (PANDER), has been recently reported to be decreased in gastric cancers with high invasiveness and metastasis." (PMID 24318988, 2014).
COVID-19 (3 papers, 2023). A disease caused by infection with severe acute respiratory syndrome coronavirus 2. "Higher FAM3B serum levels in COVID-19 patients have been linked to worse infection outcomes." (PMID 37628421, 2023). "Among these, four (CLEC4A, DSG4, FAM3B, and RARRES1) displayed significantly lower levels in both moderate and severe COVID-19, as compared to the healthy controls and the sepsis cohorts." (PMID 36829233, 2023).
esophageal cancer (3 papers, 2018 to 2022). A primary or metastatic malignant neoplasm involving the esophagus. "SLUG has been described as a survival factor in neuroblastoma, lung, and esophageal carcinomas by upregulating Bcl-2, therefore, SLUG can be the transcription factor that linked FAM3B and Bcl-2 increased expression in DU145 cells." (PMID 29357840, 2018).
Hyperglycemia (3 papers, 2016 to 2019). An increased concentration of glucose in the blood. "Chronic hyperglycemia activates FAM3B expression and couples the secretion of FAM3B and insulin under conditions of insulin resistance." (PMID 28536423, 2017). "Coincided with observations of the immunofluorescence staining, RT-qPCR analysis indicated that the mRNA expression levels of FAM3B in the VSMC layer was increased in a time-dependent manner when rats developed hyperglycemia." (PMID 28536423, 2017). "We found that FAM3B expression was induced by hyperglycemia both in vivo and in vitro." (PMID 28536423, 2017). "In the present study, we demonstrated a novel role of FAM3B in regulating VSMC proliferation and migration in response to hyperglycemia." (PMID 28536423, 2017).
prostate carcinoma (3 papers, 2018 to 2024). A carcinoma that arises from epithelial cells of the prostate gland. "FAM3B has been suggested to play important roles in the progression of many cancers, such as gastric, oral, colon and prostate cancer." (PMID 30565387, 2019). "Taken together, by activating pro-survival mechanisms FAM3B overexpression contributes to increased resistance to cell death and tumor growth in nude mice, highlighting a putative role for this cytokine in prostate cancer progression." (PMID 29357840, 2018). "In this study we show, for the first time, the role of FAM3B in tumor cell death, tumor growth, and invasiveness in prostate cancer." (PMID 29357840, 2018). "First, we verified the increased expression of FAM3B in clinical samples of prostate adenocarcinoma and three of the most representative tumor cell lines used in prostate cancer research (LnCAP, PC3 and DU145)." (PMID 29357840, 2018). "Therefore, FAM3B may become a promising molecular target for diagnosis and therapy of prostate cancers." (PMID 29357840, 2018).
colorectal tumors (2 papers, 2013 to 2018). "In the present study we confirm the anti-apoptotic effect of FAM3B in prostate tumor cells, which is in agreement with functions of FAM3B in colorectal tumors." (PMID 29357840, 2018). "Recently, Li and colleagues have identified FAM3B-258, a 258-amino acids non-secretory protein, as a novel splicing variant of FAM3B up-regulated in colon adenocarcinoma cell lines as well as in human colorectal tumors." (PMID 24285959, 2013).
Glucose intolerance (2 papers, 2014 to 2018). Glucose intolerance (GI) can be defined as dysglycemia that comprises both prediabetes and diabetes. "Also, Fam3b overexpressing mice displayed decreased insulin secretion and increased glucose intolerance." (PMID 30687391, 2018). "In contrast, glucose intolerance was improved in Fam3b knockout mice." (PMID 30687391, 2018).
insulinoma (2 papers, 2017 to 2018). "In those studies recombinant FAM3B and overexpression of FAM3B diminished cell viability and induced cell death in a βTC3 insulinoma cell line, in a dose and time-dependent manner." (PMID 29357840, 2018).
atherosclerosis (1 paper, 2017). A disease characterized by the build-up of fatty material and calcium deposition in the arterial wall resulting in partial or complete occlusion of the arterial lumen. "Targeting FAM3B will therefore serve as a novel therapeutic strategy against both atherosclerosis and cancer." (PMID 28536423, 2017).
autoimmune disease (1 paper, 2023). A disorder resulting from loss of function or tissue destruction of an organ or multiple organs, arising from humoral or cellular immune responses of the individual to their own tissue constituents. "However, further experiments are needed to explore the functional role of NF2, FAM3B, and MGMT in BD and other autoimmune diseases." (PMID 37264476, 2023).
breast carcinoma (1 paper, 2023). "Compared with normal breast tissue, FAM3B expression was different in different subtypes of breast cancer." (PMID 37251343, 2023).
esophageal squamous cell carcinoma (1 paper, 2019). Esophageal squamous cell carcinoma (ESCC) is a type of esophageal carcinoma (EC) that can affect any part of the esophagus, but is usually located in the upper or middle third. "However, little is known about the role of FAM3B in human esophageal squamous cell carcinoma (ESCC)." (PMID 30565387, 2019).
head and neck squamous cell carcinoma (1 paper, 2022). A squamous cell carcinoma that arises from any of the following anatomic sites: lip and oral cavity, nasal cavity, paranasal sinuses, pharynx, larynx, and salivary glands. "The expression of FAM3B in tumors of various systems was sometimes upregulated and sometimes downregulated, and its expression was decreased in head and neck squamous cell carcinoma (HNSC), which validated our results." (PMID 35096060, 2022).
lymph node metastasis (1 paper, 2019). "FAM3B expression was not significantly related to gender, age, differentiation, or lymph node metastasis." (PMID 30565387, 2019).
oral cancer (1 paper, 2023). "FAM3B (also called PANDER) regulates the epithelial-mesenchymal transition and has been implicated in the development of oral cancer." (PMID 37792852, 2023).
prostate adenocarcinoma (1 paper, 2018). "Our results showed that FAM3B expression was upregulated in 13/19 (70%) prostate adenocarcinoma samples compared to 11/29 (38%) non-neoplastic tissue." (PMID 29357840, 2018).
prostate tumors (1 paper, 2018). "FAM3B expression was analyzed by quantitative PCR in tumor tissue clinical samples and prostate tumor cell lines." (PMID 29357840, 2018). "Since in silico data revealed that FAM3B can be expressed in prostate tumors, we evaluated the putative role of this cytokine in prostate tumor progression." (PMID 29357840, 2018). "Nonetheless, the absence of a proliferative phenotype after FAM3B overexpression confirmed that, in contrast to its pro-apoptotic role in pancreatic β-cells, FAM3B has an anti-apoptotic role in prostate tumor cells." (PMID 29357840, 2018). "We evaluated FAM3B expression at mRNA level in prostatic normal tissue and tumor samples as well as in prostate tumor cell lines." (PMID 29357840, 2018). "We observed an increase in FAM3B expression in prostate tumor samples when compared to normal tissues." (PMID 29357840, 2018). "In order to comprehend further the role of this cytokine in prostate tumor progression, we evaluated the effects of FAM3B overexpression in the androgen-insensitive DU145 prostate tumor cell line." (PMID 29357840, 2018). "In summary, our findings reveals, for the first time, that increased expression and secretion of FAM3B in vivo may play an important role in development and progression of prostate tumors mainly by increasing Bcl-2 and Bcl-XL cell survival genes." (PMID 29357840, 2018). "Taken together, results indicate FAM3B overexpression may further enhance the tumorigenicity and even promote a malignant phenotype of established prostate tumor cells." (PMID 29357840, 2018). "Several public databases have confirmed the hypothesis that FAM3B is a pleiotropic cytokine that exerts multiple cellular functions in pancreas and liver and, likely, pathological effects when overexpressed in breast and prostate tumor tissues." (PMID 29357840, 2018). "On the other hand, it is well known that different doses of TNF induce different effects on prostate tumors, reinforcing the hypothesis that FAM3B may inhibit different mechanisms and types of cell death in DU145 cells, including autophagy and necrosis as suggested." (PMID 29357840, 2018). "Our findings showed that overexpression of FAM3B promotes in vitro tumorigenicity in DU145 cells and increases tumor growth in mice suggesting a role for FAM3B in prostate tumor progression." (PMID 29357840, 2018).
triple-negative breast carcinoma (1 paper, 2023). An invasive breast carcinoma which is negative for expression of estrogen receptor (ER), progesterone receptor (PR), and human epidermal growth factor receptor 2 (HER2). "Survival analysis showed that high FAM3B expression was associated with poor prognosis in triple-negative breast cancer." (PMID 37251343, 2023). "Survival analysis showed that overall survival was significantly shorter in triple-negative breast cancer patients with high FAM3B expression." (PMID 37251343, 2023). "Compared to normal breast tissue, the expression of FAM3B was reduced in triple-negative breast cancer." (PMID 37251343, 2023). "The results of the analysis of different datasets all showed that FAM3B was specifically highly expressed in malignant epithelial cells in the triple-negative breast cancer population." (PMID 37251343, 2023). "Single-cell analysis of triple-negative breast cancer was performed in different independent datasets, and FAM3B expression in different cells was investigated." (PMID 37251343, 2023). "Finally, FAM3B was a key biomarker affecting the prognosis of patients with triple-negative breast cancer." (PMID 37251343, 2023). "The expression of FAM3B in triple-negative breast cancer was further analyzed." (PMID 37251343, 2023). "In addition, proteomic information was obtained from the CPTAC database, and the results similarly showed that the expression level of FAM3B was lower in triple-negative breast cancer tissues." (PMID 37251343, 2023). "In addition, this study only preliminarily described the expression of FAM3B in triple-negative breast cancer and its effect on prognosis, and the specific mechanism needs to be explored by basic experiments to evaluate the reliability of the results of this study." (PMID 37251343, 2023).
type 1 diabetes (1 paper, 2018). "Initial characterization evaluating the role of FAM3B on pancreatic islets revealed induction of pancreatic β-cell apoptosis via caspase- 3 and cyclin-dependent kinase inhibitor 1A (p21) pathways, suggesting that FAM3B is a potential activator in a setting of type 1 diabetes." (PMID 29357840, 2018).
cancer (14 papers, 2016 to 2025). A tumor composed of atypical neoplastic, often pleomorphic cells that invade other tissues. "FAM3A expression was positively correlated with FAM3D, and FAM3B expression in pan-cancer (Cor = 0.10, and 0.13)." (PMID 37704682, 2023). "Although there are few studies focused on the influence of ACPP and FAM3B in cancer, we believe that the potential mechanisms of all MRMGPS-based genes in tumorigenesis and progression deserve further exploration combined with the results of our analysis." (PMID 37122696, 2023). "For FAM3B, the difference in methylation between the cancer and normal groups was insignificant, although a subset of samples showed a distinct pattern of hyper-methylation." (PMID 27016420, 2016). "FAM3B is also expressed in most normal human tissues and various cancers." (PMID 40294019, 2025). "The varied expression patterns and biological roles of FAM3B in distinct cancer types may be due to the alternative splicing." (PMID 40294019, 2025). "FAM3B plays a pivotal role in cancer initiation and progression." (PMID 40110195, 2025). "IRF1 encodes a transcription factor stimulates an immune response against tumor cells and FAM3B encodes a protein called FAM3B/PANDER, which is a hormone that regulates glucose and lipid metabolism and its expression is associated with the progression of multiple types of cancer." (PMID 40110195, 2025). "FAM3B expression was positively correlated with FAM3D expression in pan-cancer (Cor = 0.41)." (PMID 37704682, 2023). "Interestingly, FAM3B plays an important role in cancer initiation and progression." (PMID 37704682, 2023). "Studies that promoters of 886 genes involved in cancer-related pathways were abnormally hypermethylated in EBV-positive GC (AGS) cells, including FAM3B." (PMID 40110195, 2025). "As a cytokine-like gene, FAM3 family includes FAM3A, FAM3B, FAM3C, and FAM3D, and is involved in the occurrence and development of several cancers." (PMID 37056931, 2023). "The majority of the DEGs, e.g., SOX11, TBX21, FAM3B, FGF5, HNF1A, MYB, and PLAC8 have been reported to function as promoters or biomarkers in various cancer types." (PMID 34440579, 2021). "Other five genes, including BSPRY, C8ORF47, FAM3B, HOOK1 and REG1A, were clustered in Model 16 and significantly decreased during cancer progression." (PMID 30598639, 2018). "Similar associations with ERG have also been found for other FAM members, including FAM77C and FAM13A that are up regulated in the presence of ERG, or for FAM111B, FAM3B and FAM124B that are down-regulated in ERG positive cancers." (PMID 28415558, 2017). "Targeted inhibition of expression SNRPN, WNK3 and FAM3B may therefore constitute a potential therapeutic strategy for HCC and more generally for other cancers." (PMID 34006907, 2021). "FAM3B and TNFSF13 also have known implications in cancer and their altered expression may have some role in prostate tumorigenesis." (PMID 28750683, 2017). "Most of these genes are not discussed in literature and their role in EBV infection and cancer is not clear, except for IRF1 and FAM3B, that function as tumor suppressor gene and oncogene, respectively." (PMID 40110195, 2025).
infection (13 papers, 2009 to 2025). The state of being infected such as from the introduction of a foreign agent such as serum, vaccine, antigenic substance or organism. "By RT-PCR we calculated a ~2000 fold increase of FAM3B mRNA after infection with pCSC-FAM3B-derived lentiviruses." (PMID 29357840, 2018).